NR2F6 (nuclear receptor subfamily 2 group F member 6)
Diseases named in the same sentence as NR2F6 in open-access papers (continued):
Sharing a sentence is not in itself a finding about the gene and the disease.
cancer (continued). "Several reports have underscored the emphasis of NR2F6 in human cancers." (PMID 34304715, 2021). "Therefore, the critical objective for now is to firmly validate this alternative cancer immune checkpoint, NR2F6, as a unique human cancer therapeutic candidate target of the T effector cell compartment for next-generation immune-oncology regimens." (PMID 34073258, 2021). "Investigations of the inhibition of Nr2f6 in mice that used an ex vivo CRISPR/Cas9-mediated gene ablation of Nr2f6 in T cells prior to therapeutic ACT in conjunction with an approved PD-L1 or CTLA-4 ICB therapy improved this therapeutic anti-cancer activity." (PMID 34073258, 2021). "Why does the alternative and druggable NR2F6 cancer immune checkpoint appear to be important?" (PMID 34073258, 2021). "In terms of individualized adoptive therapy of NR2F6 gene-modified human T cells, the unique feature of lymphatic NR2F6 as an alternative intracellular immune checkpoint may influence combinatorial cancer therapies in the future." (PMID 31937317, 2020). "Employing CRISPR/Cas9-mediated mutagenesis technology in primary T cells, we here provide strong pre-clinical evidence that acute manipulation of lymphatic NR2F6 similarly elicits superior anti-cancer immune responses in combination with established checkpoint blockade." (PMID 31937317, 2020). "NR2F6 has been shown to participate in a broad array of functions in the mammalian system, including colon homeostasis, circadian rhythms, nociception, renin expression in kidney cells, and survival and metastasis of certain cancers." (PMID 32246891, 2020). "Hence, releasing the inhibition imposed by NR2F6 appears to be a suitable strategy to vastly enhance efficacy of cancer immunotherapy." (PMID 29670099, 2018). "This preclinical proof of concept study on the Nr2f6 gene depletion-mediated immune augmentation is envisioned as a way forward to extend the benefits of clinical immuno-oncology therapies to a larger number of cancer patients." (PMID 29670099, 2018). "We observed specific NR2F6 staining mainly in the cancer cell nuclei." (PMID 27775588, 2016). "Recent studies have indicated that NR2F6 is overexpressed in patients with certain cancers." (PMID 27775588, 2016). "We obtained expression data for 32 cancer types and DFI data for the corresponding samples and observed that higher expression of NR2F6 in CESC, KIRP, PRAD and ACC was associated with worse DFI, and higher expression of NR2F6 in the PCPG was associated with better DFI." (PMID 40424451, 2025). "Furthermore, the observed NR2F6 upregulation in biopsies of patients with defined cancer entities might thus implicate an upregulation also of lymphatic NR2F6." (PMID 34073258, 2021). "This variant is clinically interesting due to studies demonstrating that NR2F6-/- mice had enhanced IL-2 and IFN-gamma secretion, favoring T cell-mediated cancer cell elimination." (PMID 34589432, 2021). "Using germ-line knockout mice, we have identified functions of the orphan NR, NR2F6 in effector CD4+ and CD8+ T-lymphocytes during cancer progression, autoimmune responses, and immunization." (PMID 33589606, 2021). "Nuclear orphan receptor NR2F6 was upregulated in resistant EOC, which leads to sustain expression of Notch3 signaling in Cancer Stem Cells, leading to acquisition of resistant phenotype." (PMID 33968932, 2021). "Particularly, in light of an advantageous phenotypical effect of a combinatorial PD-L1/NR2F6 inhibition, we here explore the concomitant inhibition of these distinct immune checkpoints in the murine MC38 cancer model." (PMID 31937317, 2020). "Therefore, NR2F6 may be a potential cancer therapeutic target." (PMID 27775588, 2016). "We have been the first to establish an essential and non-redundant functional role of NR2F6 in T lymphocytes as an intracellular immune checkpoint during experimental autoimmunity, bacterial infection, and cancer immune surveillance and metastasis." (PMID 39920136, 2025).
cancer (continued). "We also functionally showed that Nr2f6 and JDP2 may contribute to differential expression of many ELI-D1 genes, and may contribute to increased stromal vulnerability to placental, and cancer malignancy in hemochorial vs epitheliochorial species." (PMID 40847025, 2025). "Furthermore, we evaluated the relationship between NR2F6 expression levels and OS, DSS, DFI, and PFI, finding correlations with the prognosis of various cancers." (PMID 40424451, 2025). "Particularly because there is a significant correlation of lymphatic PD-1 or CTLA-4 with lymphatic NR2F6 expression in human NSCLC patients, we wanted to determine whether acute Nr2f6 inactivation enables anti-cancer activity in vivo." (PMID 31937317, 2020). "Due to the importance of NR2F6 in other types of cancers, whether circRHOT1/TIP60/NR2F6 axis also plays a role in these cancers needs further investigation." (PMID 31324186, 2019). "In this study we provide evidence for an essential and non-redundant role of NR2F6 in critically antagonizing anti-cancer effector T-cell responses." (PMID 29670099, 2018). "However, a rigorous assessment of the physiological relevance of NR2F6 function in clinically relevant mouse cancer model systems as well as in human T-cell biology has not yet been carried out." (PMID 29670099, 2018). "However, an immunoevasive function for NR2F6 cancer-specific expression has not yet been described." (PMID 32117236, 2020).
infection (6 papers, 2021 to 2025). The state of being infected such as from the introduction of a foreign agent such as serum, vaccine, antigenic substance or organism. "In vivo, Salmonella Typhimurium loads are partially increased post-infection in anti-Sirpα treated Nr2f6-deficient mice." (PMID 40605423, 2025). "To investigate the long-term persistence and phenotype of Nr2f6-deficient OT-I T cells, we tracked transferred cells in the blood over 100 days following primary infection." (PMID 33589606, 2021). "Total Nr2f6+/+ and Nr2f6-deficient OT-I T cells were sorted between d140 and d160 after the initial LmOVA infection and were transferred into new naïve congenic recipients and infected with a high-dose of LmOVA." (PMID 33589606, 2021). "On d70 post infection, despite unaltered total cell counts in the spleen, we detected a relative as many as a threefold increase in Nr2f6-deficient CD8+CD44+OVAtet+ cells." (PMID 33589606, 2021). "The differences between isotype and IFN-γ blocked MPEC and SLEC Nr2f6-deficient OT-I T cells in blood persisted up to d28 after infection." (PMID 33589606, 2021). "Following a secondary adoptive transfer into naïve congenic mice, Nr2f6-deficient OT-I memory T cells are superior in clearing LmOVA infection." (PMID 33589606, 2021). "The results from the ACT of Nr2f6−/− OT-I T cells imply that loss of NR2F6 enhances antigen-specific memory precursor formation in vivo and effector cytokine production following acute LmOVA infection in a CD8+ T-cell intrinsic manner." (PMID 33589606, 2021). "However, whereas the initial animal weight loss in both genotypes was comparable, Nr2f6-deficient mice had regained weight faster than wild-type controls on day 7 after infection." (PMID 33589606, 2021). "Importantly, the differences between isotype and IFN-γ blocked CD127−KLRG1+ and CD127+KLRG1−Nr2f6-deficient OT-I T cells in the spleen persisted up to >d60 after infection, similar to the d70 phenotype of germ-line Nr2f6-deficient mice." (PMID 33589606, 2021). "The enhanced survival benefit of Nr2f6-knock-out mice following PbA infection has been attributed to a less compromised integrity of the BBB." (PMID 40801595, 2025). "Mechanistic research suggests that NR2F6 in T cells restrains antigen-specific effector responses, indicating that NR2F6 limits cytotoxic CD8+ T cell potential during infection." (PMID 40801595, 2025). "NR2F6 protein kept decreasing after infection, while its mRNA decreased after infection and then increased after a while." (PMID 38829910, 2024). "How and when Nr2f6 expression is changed in specific T-cell subsets during acute, memory, and recall stages of infection will need to be further elucidated in future studies." (PMID 33589606, 2021). "IFN-γ cytokine responses during the early phase of infection were significantly increased in Nr2f6−/− OT-I T cells on d3." (PMID 33589606, 2021). "In summary, we show that loss of NR2F6 in CD8+ T cells leads to augmented antigen-specific memory formation and improved effector responses upon secondary infection that are mediated through an early burst of IFN-γ." (PMID 33589606, 2021). "Suppression of IFN-γ production by NR2F6 during the initial phase of LmOVA infection subsequently controls effector vs. memory CD8+ T cell commitment, thus establishing NR2F6 as a central player in memory fate decision." (PMID 33589606, 2021). "Despite unaltered total OT-I T cell numbers in the spleen, IFN-γ+ cell numbers were enhanced, suggesting a more robust IFN-γ response in Nr2f6−/− OT-I T cells upon re-infection with the same pathogen." (PMID 33589606, 2021). "Additionally, NR2F6 plays a pivotal role in regulating immune system activation during infection and oncogenesis." (PMID 40801595, 2025). "To investigate whether enhanced IFN-γ production is a driver of increased memory formation of Nr2f6-deficient OT-I T cells, we injected an IFN-γ blocking antibody within 24 h after LmOVA infection." (PMID 33589606, 2021).
infection (continued). "Therefore, to determine the early and causal factor(s) that alter precursor and long-term memory formation in Nr2f6-deficient CD8+ T cells, we investigated OT-I T cell responses 24 h or 3 days after infection." (PMID 33589606, 2021). "To investigate the effector functions of memory Nr2f6-deficient CD8+ T cells, we stimulated splenocytes ex vivo on d70 post infection either in an antigen-independent manner using phorbol 12,13-dibutyrate (PDBu) and ionomycin (P/I) or in an antigen-specific manner with the SIINFEKL (N4) peptide." (PMID 33589606, 2021). "Although we did not observe any change in CD119 (IFN-γR) expression in Nr2f6-deficient OT-I cells, by d7 after infection, SLECs had accumulated at the expense of MPECs in the spleens of anti-IFN-γ treated mice, resulting in similar levels as compared to animals that had received isotype control." (PMID 33589606, 2021). "Of note, Nr2f6-deficiency did not impact pathogen clearance 3 days post-LmOVA infection." (PMID 33589606, 2021). "In contrast, by d140 after infection, we could not observe any differences in splenic Nr2f6-deficient OT-I CD127+KLRG1−, Tcm, or Tem populations." (PMID 33589606, 2021). "Our data with the LmOVA infection model show that lack of Nr2f6 leads to increased IFN-γ expression, independently of T-bet19,22." (PMID 33589606, 2021). "Although we did not investigate Nr2f6 expression within SLECs and MPECs during the early and late phases of LmOVA infection, it does seem plausible that expression is higher in Tem during acute LCMV, i.e., NR2F6 is acting as a brake on cells with high potential to damage surrounding tissue." (PMID 33589606, 2021).
bacterial infection (2 papers, 2021 to 2024). "Here, we show that loss of the nuclear orphan receptor NR2F6 in germ-line Nr2f6-deficient mice enhances antigen-specific CD8+ memory formation up to 70 days after bacterial infection with Listeria monocytogenes (LmOVA) and boosts inflammatory IFN-γ, TNFα, and IL-2 cytokine recall responses." (PMID 33589606, 2021). "NR2F6 encoded a nuclear orphan receptor, which is involved in antigen-specific CD8 + memory formation after bacterial infection." (PMID 38902725, 2024). "Some overexpressed genes in BM samples are associated with infections, such as ASRGL1, NR2F6, and OLFML3 for bacterial infection." (PMID 38902725, 2024).
hematologic malignancies (1 paper, 2023). "All these results indicated that NR2F6 expression was associated with more malignant biologic process as other solid and hematologic malignancies." (PMID 37575237, 2023).
inflammation (1 paper, 2018). Aberrant reaction of the microcirculation characterized by movement of fluid and leukocytes from the blood into extravascular tissues. "On a transcriptional level, Muc2 mRNA expression was reduced in steady-state Nr2f6−/− colon specimens, although not significantly, but a strongly reduced Muc2 mRNA expression level in Nr2f6−/− colons was observed on day 7 on DSS treatment-induced intestinal inflammation." (PMID 28779026, 2018).
metabolic disease (1 paper, 2024). A congenital disorder (due to inherited enzyme abnormality) or acquired (due to failure of a metabolically important organ) disorder resulting from an abnormal metabolic process. "Our discoveries establish Nr2f6 as a novel regulator of muscle contraction and metabolism and allude to a potential therapeutic strategy for muscle wasting and metabolic diseases." (PMID 38682559, 2024).
NR2F6 also shares sentences with these, for which no sentence is quoted: colorectal cancer (3 papers); infectious disease (3); adenocarcinoma (2); Alzheimer disease (2); bladder cancer (2); head and neck cancer (2); head and neck squamous cell carcinoma (2); Lymph Node Metastasis (2); pancreatic cancer (2); acute leukemia (1); adrenal hypoplasia congenita (1); alcohol abuse (1); chronic kidney disease (1); Cirrhosis (1); clear cell carcinoma of the kidney (1); crescentic glomerulonephritis (1); dermatomyositis (1); dyslipidemia (1); endometrial adenocarcinoma (1); endometriosis (1); gastric adenocarcinoma (1); helminthic infections (1); Hepatic fibrosis (1); hereditary spastic paraplegia (1); Hyperinsulinemia (1); injury (1); Insulin resistance (1); intestinal inflammation (1); large cell carcinoma (1); liver diseases (1).
A further 6 diseases each share a sentence with NR2F6 in 1 paper.